IL17A (interleukin 17A)
Diseases named in the same sentence as IL17A in open-access papers (continued):
Sharing a sentence is not in itself a finding about the gene and the disease.
colitis (continued). "IFN-γ–deficient Th17 cells maintained their Th17 phenotype but failed to induce colitis in mouse models, and IL-17A+IFN-γ+CD4+ T cells were considered to be more pathogenic." (PMID 35784693, 2022). "TIGIT deficiency impairs IL-17A production in CD69+CD103− CD4+ TRM cells specifically, resulting in lower disease activity index and reduced pathological injury in mice with DSS-induced colitis." (PMID 35844584, 2022). "Notably, the number of CD4+ T cells expressing IL-17A was significantly increased in mice with DSS-induced colitis, while numbers of CD4+ T cells expressing IFNγ remained unchanged." (PMID 35844584, 2022). "CD69+CD103− CD4+ TRM cells could play an important role in controlling DSS-induced colitis by producing IL-17A." (PMID 35844584, 2022). "Moreover, interfering with Th17 responses by neutralizing IL-17A attenuates the progression of colitis and asthma 45,4." (PMID 33754076, 2021). "Moreover, antibody neutralization of IL-1β protected mice from Helicobacter hepaticus-triggered colitis by limiting the accumulation of granulocytes and IL-17A-producing innate lymphoid cells." (PMID 33562334, 2021). "In DSS-induced colitis mice treated with miR-19a mimic, colon tumor numbers, sizes and tumor loads are higher compared to the control group; pro-inflammatory cytokines, including IL-1β, IL-6, IL-17a, IFN-γ and TNF-α are also upregulated." (PMID 33921348, 2021). "Antibody-mediated IL-17A neutralization blocked ETBF-induced colitis and tumorigenesis." (PMID 34299314, 2021). "Moreover, we observed enhanced expression of IL-17A, IFNγ and TNFα in colon tissues from the colitis mice (DSS-treated) given the EBV DNA compared to the other groups." (PMID 34210024, 2021). "This might explain the opposing effects observed in clinical trial in active crohn’s disease where IL-17A inhibition resulted in worsening of colitis, but treatment with anti-IL-12/IL-23p40 as well as p19 inhibition improved inflammation." (PMID 34267743, 2021). "In this stage of colitis, food intake with βGh (CβGh+ group) up-regulated the expression of the Il13, Il21, Il27, and Lta genes and down-regulated the expression of the Il1a, Il11, and Il17a genes." (PMID 33923129, 2021). "In addition, epithelial PBLD deficiency in TNBS-induced colitis was associated with decreased CD4+ Foxp3+ cells (a marker of T regulatory cells) and increased IL-17A+ cells." (PMID 34059646, 2021). "However, after treatment with L.p R3 or/and MSLZ, the anti-inflammatory factor IL-10 levels were increased and the value of IL-10/IL-17A ratio was significantly increased (p < 0.05) in the DSS-induced colitis mice." (PMID 34407839, 2021). "In contrast to IL23, different murine models of colitis suggest a protective role for IL17A." (PMID 33859636, 2021). "Furthermore, while experimental colitis upregulated inflammatory genes in the colon, including Tnfa, Il6 and Ifng, UC patients also upregulated IL17A and IL10, followed by a slight increase in IL4 and mevalonate kinase (MVK) expression." (PMID 34434187, 2021). "IL23 plays an important role in T-cell mediated colitis and promotes the production of Il17a." (PMID 33202783, 2020). "Increased level of IL-17A and reduced level of IL-17F alleviated colitis in mice consequently." (PMID 32391010, 2020). "In addition, it has been documented that intestinal Il-1β and Il-17A produced by ILCs play an important role in the development of Hh-induced colitis in RAG2 mice." (PMID 33255175, 2020). "However, in the experimental colitis mouse model neutralization of both IL‐17A and IL‐17F ameliorated colitis, whereas neutralization of IL‐17A or IL‐17F alone had limited effect." (PMID 31850514, 2020). "Neutralization of IL-17A reduced the severity of colitis in CD4CreTTPf/f mice." (PMID 32922402, 2020). "Furthermore, the CD4CreTTPf/f mice were prone to DSS-induced colitis with higher levels of serum IL-17A and TH17 cells in mesenteric lymph node (LN) than WT mice." (PMID 32922402, 2020).
colitis (continued). "Elevated Arg-1 enhanced IL-17A expression but decreased IL-17F levels and contributed to attenuating immune response in the colorectum, thereby maintained intestinal barrier integrity and ultimately alleviating colitis." (PMID 32391010, 2020). "Interestingly, this is consistent with the elevated expression of IFN-γ and IL-17A that we observed in colitis-induced Villin-Cre;Gankyrinf/f mice, which showed augmented inflammation." (PMID 31941439, 2020). "longum induced fewer IL-17A+ lymphocytes and protected against colitis compared to EPS−B." (PMID 32351514, 2020). "Indeed, IL-17A was protective against colitis mainly by ensuring integrity of the gut mucosa, while IL-17F was proinflammatory." (PMID 33244315, 2020). "Altogether, Batf initiates Il17a expression to induce ILC3 activation leading to colitis induction." (PMID 32796851, 2020). "Colitis mitigation in Rag1−/−Irf4−/− T cell recipients resulted in reduced frequencies and absolute numbers of IL-17a-producing T cell subsets in MLN and cLP possibly due to a regulation of conventional dendritic cell subset 2 (cDC2) known to impact Th17 differentiation." (PMID 33584655, 2020). "Likewise, a specific B. adolescentis strain protected mice from DSS-induced colitis by increasing IL-10 levels, up-regulation of regulatory T-cells (Treg) and decreasing IL-17A positive T-cells." (PMID 32610452, 2020). "Notably, inhibition of IL-17A has been shown to worsen colitis in mouse models and blocking of IL-17A and IL-17RA with the monoclonal antibodies SEC and BRO, respectively, in patients with CD not only failed efficacy, but appeared to worsen disease activity." (PMID 32459816, 2020). "Our data thus far suggests that HSD decreases IL-17A production and colitis." (PMID 33126615, 2020). "Furthermore, IFNγ appears to be the most critical factor driving colitis while IL-17A and IL-13 play a less important role." (PMID 33603753, 2020). "One of the possible reasons for the difference in the outcome of anti-IL-17A therapy between acute and chronic colitis models may be the different effects of cytokines depending on the phase of colitis." (PMID 31941937, 2020). "At the same time, Ang II can also be used as an inflammatory factor to upregulate the level of IL-17A, further aggravating the inflammatory response, which may be an important pathogenesis of experimental colitis in mice." (PMID 33100902, 2020). "IL-17A and IL-17F play critical roles in the intestinal immune response during colitis." (PMID 32391010, 2020). "In mouse models, IL-17A or IL-17RA blockade resulted in colitis exacerbation." (PMID 31488067, 2019). "In mice IL-17A expression has been proposed to benefit intestinal barrier function and IL-17F to weaken intestinal integrity, since IL-17A inhibition exacerbates induced colitis and IL-17F suppression is protective." (PMID 32010094, 2019). "In addition, M2b macrophage exosomes increased the percentage of Treg cells in mice with DSS-induced colitis and reduced pro-inflammatory cytokine (IL-1β, IL-6, and IL-17A) production in the colon of mice with DSS-induced colitis." (PMID 31749791, 2019). "In support of this interpretation, a previous study demonstrated that mice selectively lacking the Foxp3+RORγt+ Treg subset develop elevated intestinal IL-17A responses at steady state and experience exacerbated immunopathology in a chemically-induced colitis model." (PMID 31889073, 2019). "Furthermore, the severity of murine colitis was enhanced with anti-IL-17 neutralizing antibody treatment or IL-17A knockout." (PMID 29849501, 2018). "However, compared to WT or heterozygous controls, intestinal CD4+ T cells of Alpk1−/− mice were highly skewed towards a Th1 phenotype (IFN-γ+ IL-17A–) following induction of colitis, as measured by cell frequency and IFN-γ expression per cell." (PMID 30228258, 2018). "IL-17A has been shown to be a driving effector response for colitis in mice." (PMID 29466406, 2018).
colitis (continued). "Genome-wide association scan data indicate a role played by Th17 cells in IBD, and a combined blockade of IL-17A and IL-17F could obviously prevent the development of experimental colitis." (PMID 30563054, 2018). "Indeed, although Th17 cells are generally associated with a pro-inflammatory response in autoimmunity, IL-17A can have very different effects during colitis." (PMID 30619314, 2018). "The protective effects of GLP on colitis induced by DSS were associated with an increase in B cells but a decrease in T cells, mainly a decrease in 17A-producing CD4+ T-LPLs, and a decrease in the production of IL-17A and IL-4 in LP." (PMID 29888292, 2018). "Moreover, IL-23 which is mainly secreted by resident monocytes stimulates innate lymphoid cells to secrete IL-17 and loss of IL-23 receptor led to lower IL-17A expression during DSS-induced colitis." (PMID 29261815, 2017). "The level of Th1 cytokine-IFN-γ was significantly higher, but the levels of Th2 cytokine-IL-4, IL-5 or IL-13, and Th17 cytokine-IL-17A were greatly lower in colonic LP of IL-21RKO mice after DSS-induced colitis as compared with those in C57BL/6 mice (**P < 0.01 or ***P < 0.001)." (PMID 27545302, 2016). "However, neutralization of IL-17A (by antibody treatment or genetic knockdown) leads to exacerbated intestinal inflammation in the dextran sulphate sodium (DSS) colitis model." (PMID 27152519, 2016). "However, blockade of IL-17A failed to modify anti-CD40-induced systemic or intestinal disease, indicating that IL-17A is dispensable for development of acute colitis in this model." (PMID 26780670, 2016). "By contrast, double blockade of IL-17A and IL-22 reduced colitis severity, indicating that these cytokines may play a redundant role in driving intestinal inflammation possibly through shared effects on intestinal epithelial cells." (PMID 26780670, 2016). "The role of IL-17A may also be tissue specific; in dextran sodium sulphate induced-colitis, IL-17 is protective, since neutralization of IL-17 worsened colitis while CD25/IL-17 DKO mice had more severe autoimmune biliary disease." (PMID 25889094, 2015). "IL-17A+ γδ T cells are also required for the resolution of eosinophilic inflammation after allergen challenge in mice and IL-17A is also protective in several mouse models of colitis." (PMID 26135595, 2015). "IL-17A plays a proinflammatory role in acute TNBS (Trinitro-Benzene-Sulfonic Acid)-induced colitis." (PMID 25133396, 2014). "Instead, the accumulation of IFNγ+, IL-6+ and IL-17A+ IEL cells in prolapsed CD4cre:PP4f/f mice may only occur during the latter phase of colitis pathogenesis." (PMID 24904742, 2014). "Similarly, the administration of a neutralizing IL-21 antibody to DSS-colitis mice decreased the colonic T-cell infiltrate and the production of IL-6 and IL-17A in the inflamed colonic tissue." (PMID 25101191, 2014). "Considering it's central role in the development of colitis, altered regulation and secretion of IL-17A might contribute to the reduced inflammatory response in Btk-/- animals." (PMID 25379804, 2014). "In addition, we blocked IL-17A in mice with TNBS- induced colitis in vivo and found that this enhanced CXCL11 and IL-12P35 mRNA expression by CECs." (PMID 24586980, 2014). "Interestingly, our data clearly showed that administration of IL-17A attenuated the ability of CECs from TNBS-induced colitis mice to induce colitis when transferred into recipients and decreased the expression of CXCL11, IL-12P35, and IFN-γ." (PMID 24586980, 2014). "Collectively, these data indicate that JCM 1222T negatively regulate epithelial costimulatory molecules, and this effect might be attributed, at least in part, to suppression of IL-17A in DSS-induced colitis." (PMID 24255712, 2013). "However, in other systems, such as DSS colitis, the function of IL-17F appears to oppose that of IL-17A, exacerbating disease." (PMID 23405904, 2013).
colitis (continued). "Indeed, 71% (5/7) of anti-IL-17A-treated mice had complete resolution of colitis (colitis score = 0)." (PMID 23063332, 2012). "In the adoptive transfer model, transfer of RORγ-null T cells do not induce colitis; however, lymphocytes from IL-17A-deficient mice induced severe colitis." (PMID 21931623, 2011). "An anti-inflammatory effect of IL-17A has also been seen in the T cell-transfer colitis model." (PMID 22082127, 2011). "Notably, IL-17A+IFN-γ+ CD4+ T cells are prominent in T cell-dependent colitis models and have also been recovered from the intestinal lesions of human CD patients." (PMID 20732640, 2010). "Furthermore, the disruption of IL-17RA signaling in enterocytes reduced the pathology of DSS-induced colitis and IL-17A and -F are known to induce enterocyte expression of antimicrobial peptides and numerous pro-inflammatory cytokines." (PMID 21124903, 2010). "We found that cytokine-neutralization of IL-17A and/or F or a genetic IL-17RA-deficiency did not affect S. Typhimurium colitis, i.e. pathogen colonization of the mLN, degree of intestinal inflammation and the patterns of cytokines induced by 12 h p.i." (PMID 21124903, 2010). "Therefore, IL-17A may play the dominant role in Tak1ΔM/ΔM mice to maintain the resistance against colitis, while IL-22 provides an independent and supportive function." (PMID 40749055, 2025). "Colitis-associated epithelial injury and intestinal leakage can be exacerbated in the absence of IL-17A signaling and reveals that IL-17A serves a beneficial role in the intestinal epithelium by helping to maintain the epithelial tight-junction barrier during inflammation." (PMID 38790988, 2024). "Because IL-17A and IL-22 are critical for maintaining intestinal barrier function, we asked whether C. tropicalis colonization modulates intestinal epithelial barrier function and integrity during colitis in vivo." (PMID 39462273, 2024). "To verify our hypothesis that IA-0130 suppresses the excessive expression of pro-inflammatory cytokines, we analyzed the mRNA and protein expression of pro-inflammatory cytokines, TNF-α, IL-1β, IL-6, and IL-17A, which are important in colitis development and maintenance." (PMID 38916850, 2024). "Thus, while WT, Ifng−/−, and Il17a−/− MP cells exhibited unaltered degree of inflammation, deficiency in IFN-γ in the same cells significantly inhibited colitis when IL-17A was blocked, arguing that MP cell–derived IFN-γ plays an important role in the response generation." (PMID 39630890, 2024). "Therefore, ICB-based immunotherapeutic efficacy could be upgraded by blocking IL-17A activities when treatment-related colitis occurred, even the adverse events were minor." (PMID 37605139, 2023). "In a model of DSS-induced colitis, we could not associate either IFNγ or IL-17A production by cLP ILC2 with loss of CD90 expression." (PMID 37114052, 2023). "By deleting Senp2 in T-cell lineages in mice, we demonstrate that the lack of Senp2 exacerbates the severity of experimental colitis, which is linked to elevated levels of GM-CSF+IL-17A+ pathogenic Th17 cells and more severe dysbiosis of the intestinal microbiome." (PMID 37301920, 2023). "Interestingly, the CRAC channel inhibitor BTP2 or CM4620 was shown to significantly reduce the production of inflammatory cytokines (such as IFNγ, TNF, IL-17A, IL-13, and IL-4) from human intestinal T cells, B cells, ILCs and myeloid cells, and improve colon inflammation in a mouse model of IBD." (PMID 36459135, 2023). "Furthermore, another recent study discovered that Eggerthella lenta could promote colitis in mice by activating Th17 cells and promoting IL-17a production through its expression of a drug-metabolizing enzyme, Cardiac glycoside reductase (cgr2)." (PMID 36590401, 2022).
colitis (continued). "Albeit it has been shown that TIGIT had T-cell–intrinsic inhibitory functions, the decreased expression of CD155 in the colon of TIGIT−/− mice could lead to reduced TIGIT/CD155 interaction, which might contribute to decreased IL-17A production during DSS-induced colitis in the current study." (PMID 35844584, 2022). "However, increased IL17A levels are not necessarily associated with worse symptoms in all models of acute colitis; its effects are heavily dependent on the surrounding circumstances." (PMID 36123355, 2022). "Therefore, recruitment of IL-17A-secreting Tγδ cells protects mice against DSS-induced colitis." (PMID 35677043, 2022). "Moreover, a murine model with CD4+ T cells lacking the IL23R has revealed that IL23R signaling induces colitis, associated with the induction of IFNγ and IL17A co-expressing cells." (PMID 33859636, 2021). "Additionally, Bifidobacterium has been reported to alleviate DSS-induced colitis by suppressing the IL-17A response and prevent intestinal inflammation through the induction of intestinal IL-10-producing Tr1 cells, further confirming the protective role of Bifidobacterium in colitis." (PMID 33748287, 2021). "IFN-γ and IL-17A mRNA levels tended to decrease in the colon of the tannin diet group, but not significantly, which suggested that persimmon-derived tannin mainly affected innate immunity or the microbiota rather than the development and/or functions of effector T cells in the colitis model." (PMID 33790314, 2021). "In addition to its pro-inflammatory function, IL-17 has a key role in the maintenance of barrier properties of epithelial tissues, and clinical trials targeting IL-17A and IL-17RA in patients with Crohn’s disease had to be terminated due to exacerbation of colitis." (PMID 32906785, 2020). "Furthermore, neutralization of IL-17A reduced the severity of colitis." (PMID 32922402, 2020). "Colitis is characterized by expression of both pro-inflammatory cytokines, including tumour necrosis factor-alpha (Tnfa), interleukin 1-β (Il1b), and interleukin 17 A (Il17a), and anti-inflammatory cytokines, including interleukin 10 (Il10) and interleukin 22 (Il22)." (PMID 32042047, 2020). "In addition, the DSS-associated colitis immune alterations were also more obvious in the Z5D group compared with the K6D or control groups, as shown by increased serum levels of proinflammation cytokines, such as TNF-α, IFN-γ, and IL-17a (P < 0.05)." (PMID 32670220, 2020). "Therefore, Ifng−/− CD4 CD45RBhi T cells were transferred into Rag1−/−Ifng−/− mice for colitis induction and recipient mice were treated with either isotype control antibody or neutralizing antibodies against IL17A and against IL17F twice a week for the duration of the experiment." (PMID 29416538, 2018). "Conversely, and opposed to the tissue-protective effects described for IL-17A and IL-22, it has been reported that IL-17F-deficient mice develop milder DSS-induced colitic symptoms than wild-type animals, thus suggesting that IL-17F exacerbates inflammation in this experimental model of colitis." (PMID 25101191, 2014). "In contrast, pioglitazone-treated mice not only recovered from colitis and its associated weight loss, but also showed a switch from a predominant Th17 into an iTreg phenotype characterized by increased expression of FOXP3 and decreased IL17-A and RORγt in CD4+ T cells of the colonic LP and MLN." (PMID 23592971, 2013). "Furthermore, a protective role was also proposed for IL-17A in a T-cell transfer model of colitis." (PMID 22506136, 2012). "IBM attenuated colitis, improving DAI, preventing colon shortening, and ameliorating histopathology, with decreased IL-23 and IL-17A and increased IFN-β and GM-CSF." (PMID 41823856, 2026). "Matrix metalloproteinase (MMP)-10, IL-17A, FGF-19, IL-10, and CXCL9 were increased in patients with exclusive colonic inflammation, that is, UC and colonic CD, compared to patients with exclusive ileal inflammation, that is, ileal CD." (PMID 39495605, 2025).